INS (insulin)
Diseases named in the same sentence as INS in open-access papers (continued):
Sharing a sentence is not in itself a finding about the gene and the disease.
Hyperglycemia (continued). "Another parameter for the glycemic control was the occurrence of hypoglycemia and hyperglycemia, with some degree of intolerability to both insulin regimens, and breaking the fast as an ultimate measure." (PMID 33425548, 2020). "Hyperglycemia, insulin insensitivity, and low IGF1 levels in extremely preterm infants are associated with an increased risk of retinopathy of prematurity (ROP), but the interactions are incompletely understood." (PMID 33004691, 2020). "Various studies in human medicine have shown that vaccinations during therapy with insulin or oral antidiabetic drugs are effective and safe, although, in poorly controlled patients, hyperglycemia is assumed to strongly compromise the immune system." (PMID 32961758, 2020). "Generally, T2DM is characterized by hyperglycemia and elevated free fatty acid levels, which contribute to the dysfunction and death of pancreatic β-cells and lead to insufficient insulin secretion." (PMID 32377518, 2020). "Treatment of db/db mice with a VDAC1 inhibitor, VBIT-4, prevented hyperglycemia, stimulated insulin secretion, and maintained normal glucose tolerance." (PMID 32093016, 2020). "In the USA, both the ADA and ACOG recommend insulin as the first line for control of hyperglycemia in patients with GDM." (PMID 33371325, 2020). "Although commonly used anti-diabetic therapies such as insulin and metformin can control hyperglycemia, their limited efficacy in protecting the myocardium necessitates further investigations into alternative remedies." (PMID 32325968, 2020). "In vivo insulin treatment rescued hyperglycemia and insulin-treated diabetic mice maintained normo-glycemia (116 ± 61 mg/dL), following the insertion of the continuous release subcutaneous osmotic insulin pumps." (PMID 32903422, 2020). "DM is a group of metabolic diseases characterized by hyperglycemia resulting from defects in insulin secretion, insulin action, or both." (PMID 32085626, 2020). "For example, baicalein, one of the main active compounds in Scutellariae Radix, significantly improved hyperglycemia, glucose tolerance, and blood insulin levels in obese diabetic mice by directly modulating pancreatic β-cell function." (PMID 32245128, 2020). "We examined blood glucagon levels in RIP-CreΔLEPR-LEP, however, i.c.v. leptin injection lowered blood glucagon in insulin-deficient RIP-CreΔLEPR mice, while RIP-CreΔLEPR-LEP still showed hyperglycemia." (PMID 33071988, 2020). "As a truth, continuous subcutaneous insulin infusion via insulin pump is a common choice for hyperglycemia management at LHLH but is rarely used at SMH." (PMID 32267843, 2020). "In high-fat-diet-treated mice, chronic UAG overexpression prevented hyperglycemia and IR and altered insulin signaling." (PMID 32963741, 2020). "Collectively, these studies demonstrated that BlB supplementation protected against HFD/HCD-induced IR hyperglycemia, pro-inflammatory responses, oxidative stress, adipocyte death, and improved insulin sensitivity, with mixed results for HFD-induced BW gain." (PMID 32825710, 2020). "Conversely, T2DM is intimately correlated with long-term insulin resistance and compensated hyperinsulinemia, which progresses to T2DM when the insulin response to glucose demands becomes insufficient, leading to insulinopenia with consequent hyperglycemia." (PMID 32774865, 2020). "Taken together, these results indicate that liraglutide ameliorates hyperglycemia both in fasting and fed conditions but acting differently to insulin." (PMID 32477262, 2020). "Taken together, these data suggest that muscle can secrete BDNF into the circulation and plasma BDNF levels regulate insulin secretion in situations of hyperglycemia as observed in isolated islets." (PMID 32327658, 2020). "A total of 382 treatment-naïve patients with recently diagnosed T2DM were randomized to receive insulin or oral hypoglycemic agents for rapid initial correction of hyperglycemia." (PMID 32489427, 2020).
Hyperglycemia (continued). "A 47-year-old Asian Indian woman presented with uncontrolled hyperglycaemia and osmotic symptoms despite multiple oral antidiabetic medications and insulin." (PMID 33304668, 2020). "Researchers then investigated the effect of hyperglycaemia on the DNA methylation of the insulin promoter with clonal rat insulinoma-derived INS 832/13 β cells." (PMID 32653024, 2020). "SGLT‐2is have been shown to decrease hyperglycaemia to a similar extent in both T1DM and T2DM, improve insulin sensitivity in T2DM,111 promote weight loss and decrease tissue inflammation and subsequent effects on the kidneys." (PMID 32704554, 2020). "Persistent hyperglycemia reduces Cx36 mRNA levels in insulin-secreting cells in a rat model of continuous glucose infusion, and blocking the cAMP/PKA pathway attenuates this effect." (PMID 33379194, 2020). "Decreased insulin synthesis and reduced secretion are both involved in β-cell failure contributing to hyperglycemia." (PMID 33195350, 2020). "As beta cell dysfunction further deteriorates, beta cells cannot meet the persistent demand for increased insulin biosynthesis and secretion in response to persevering elevated glycemia i.e., chronic hyperglycemia." (PMID 33182622, 2020). "Two main approaches to prescribing insulin are based on the specific timing of recurrent hyperglycemia." (PMID 33371325, 2020). "This is due to the fact that utilizations of glucose by the fetal cells becomes high since maternal hyperglycemia increase fetus blood glucose level which further increase fetal insulin secretions leads to macrosomia." (PMID 33170888, 2020). "The administration of L. rhamnosus BSL and L. rhamnosus R23 for 30 days significantly improved hyperglycemia and insulin sensitivity, specifically, in decreasing FBG and improving glucose intolerance, as seen by OGTT." (PMID 32399477, 2020). "ZDF rats become insulinopenic (insufficient secretion of insulin) at 14 weeks of age due to pancreatic β-cell insufficiency and the male rats develop gender-specific hyperglycemia by 10–12 weeks of age." (PMID 32655492, 2020). "Animal studies have demonstrated that hyperglycemia suppresses LRP1 expression and that its deficiency in neurons leads to the impairment of insulin signaling pathways and glucose uptake." (PMID 33013281, 2020). "This abnormal ROS imbalance contributes to mitochondrial dysfunction that affects insulin secretion and insulin sensitivity at target tissues, leading to hyperglycemia." (PMID 32384625, 2020). "Within 1–10 min following a meal, hyperglycaemia prompts beta cells to secrete a small fraction (<5%) of their insulin content." (PMID 32894308, 2020). "Among patients with T2DM who initiated BI therapy due to uncontrolled hyperglycaemia by OADs, the proportion of insulin discontinuation was high within 6 months." (PMID 32318640, 2020). "In streptozotocin-injected neonatal hyperglycemia oxygen-induced retinopathy pups, insulin serum levels were significantly decreased at P12 compared with PBS-injected normoglycemic oxygen-induced retinopathy controls (P = 0.0007)." (PMID 33004691, 2020). "Ghrelin deletion in obese mice decreases hyperglycemia and enhances glucose-induced insulin secretion, thereby improving insulin sensitivity in peripheral tissues." (PMID 32565790, 2020). "C57bl/6J (db/db) and 129/J (db/db) mice are obese and initially develop mild hyperglycemia at 8–10 weeks of age, but this resolves by 20–30 weeks, concurrent with increased insulin production and β‐cell mass." (PMID 33113267, 2020). "IR, besides contributing to hyperglycemia, can also decrease the insulin-induced vasodilation and, potentiate its alternative vasoconstriction pathway." (PMID 32187237, 2020). "It was also postulated that the stress response to high altitude dominates exercise-enhanced insulin sensitivity, resulting in relative hyperglycemia." (PMID 33015195, 2020).
Hyperglycemia (continued). "Increasing physical activity of varying duration and intensity improves postprandial glucose handling, long-term glycemic control, time spent in hyperglycemia, and insulin sensitivity in diabetic patients." (PMID 32215273, 2020). "When utilized, insulin infusion was effective in controlling hyperglycaemia for the majority of patients receiving this therapy within 12 h of initiation." (PMID 32612144, 2020). "The clinical characteristics of patients with T2DM are decreased insulin production and impaired insulin function, which leads to persistent hyperglycemia." (PMID 32847055, 2020). "The data from the current study, showing higher plasma fructosamine concentrations in the Group MEN (i.e., prolonged hyperglycemia), indicate that insulin sensitivity and glucose homeostasis are early affected after ovarian failure." (PMID 32932852, 2020). "Ghasemi reported osmotic changes during hemodialysis, induced by hyperglycemia before the starting of insulin therapy, played an important role in lens overhydration by sorbitol accumulation." (PMID 31269848, 2019). "Oral administration of STZ-induced, diabetic, Wistar rats with curcumin (100 mg/kg b.w./day) for 8 weeks resulted in a reduced serum glucose levels and increased insulin levels, indicating reduced hyperglycemia." (PMID 31881654, 2019). "Rapamycin increased insulin sensitivity and reduced weight in three models, decreased hyperinsulinemia in two models, and elevated hyperglycemia in one model." (PMID 31406105, 2019). "We have previously demonstrated an increase in expression of PEPCK, PGC1a and defects in the hepatic insulin-AKT-FoxO1 signaling pathway resulting in overt hyperglycemia and IR in response to PM2.5 inhalation." (PMID 31757983, 2019). "The damage of β-cells by hyperglycemia-induced oxidative stress ultimately leads to apoptotic cell death and reduces insulin secretion." (PMID 30769910, 2019). "In the first scenario (Scenario I), the patients are assumed to have doubled CR and halved BR profile segments compared with the default values in the simulator; both of these settings will lead to increased hyperglycemia due to conservative insulin delivery." (PMID 30680319, 2019). "In non-diabetics, GIP stimulates glucagon secretion during hypoglycemia and potentiates insulin secretion during hyperglycemia." (PMID 31443356, 2019). "After 15 days of dark chocolate intake, an increase in vasodilation was observed (by increasing NO availability), insulin sensitivity and β-cell function, as well as a decrease in BP and hyperglycemia." (PMID 30935075, 2019). "On the 28th day, he was diagnosed as having hyperglycemia (serum glucose level was 496 mg/dL) by blood examination and treatment with regular daily insulin injections (1.0 unit/kg per day) was started immediately." (PMID 31366392, 2019). "Taken together, the 3-month-old hIAPP pigs showed hyperglycemia, decreased glucose utilization, and increased insulin tolerance, indicating successful T2DM modeling in hIAPP pigs." (PMID 31659151, 2019). "Insulin administration ameliorates hyperglycemia and lipid abnormalities in many DM patients, but it is difficult and inconvenient for the patients to inject insulin themselves." (PMID 31100973, 2019). "Damage to the beta-pancreatic cells affects the release of insulin which results in a condition known as hyperglycaemia." (PMID 31513755, 2019). "PPE ameliorated hyperglycemia and dyslipidemia, and improved glucose tolerance and insulin sensitivity in diabetic rats." (PMID 31887984, 2019). "T2DM is a complex metabolic disease characterized by defects in insulin action, progressive β-cell dysfunction and hyperglycemia." (PMID 30975165, 2019). "Type 2 diabetes (T2D) results from a combination of insufficient insulin secretion and defective glucagon secretion and culminates in hyperglycemia." (PMID 30415925, 2019).
Hyperglycemia (continued). "After the initial year of insulin analog treatment, the patient began to experience frequent morning hypoglycemic attacks and day-time hyperglycemia." (PMID 30621663, 2019). "The insulin-antagonistic effects of GH were initially described about 85 years ago following the observation that hypophysectomy performed in dogs improved hyperglycemia and experimental diabetes." (PMID 31417493, 2019). "The two standard protein/energy groups and two high protein/energy groups had very similar prescribed intakes as part of the NPN guideline and the management of PN intolerance (insulin treatment for hyperglycaemia and triglyceride monitoring) was the same." (PMID 31509953, 2019). "Another study demonstrated that there is an increased insulin sensitivity in the liver and muscle, which improved hypertriglyceridemia and hyperglycemia in diabetic rats when they were fed 300 mg/kg of PA daily for 4 weeks." (PMID 31228942, 2019). "A high fiber intake can also provide beneficial metabolic effects, such as an attenuation of hyperglycemia, improved insulin sensitivity, and hypercholesterolemia, which, in turn, are related to enhanced physical performance." (PMID 30700281, 2019). "The extracts of kaempferol from Bauhinia forficate leaves reduce hyperglycemia and enhance glucose uptake, mimicking the action of insulin." (PMID 31480505, 2019). "DM is a common metabolic disorder characterized by hyperglycemia, which occurs due to impaired insulin secretion in the pancreas." (PMID 31652041, 2019). "Although SUR1−/− rats showed glucose intolerance for KATP channel dysfunction to secret sufficient insulin, enhanced peripheral insulin responsiveness can provide a direct account for survival and protection from hyperglycaemia." (PMID 30616503, 2019). "T2DM is characterized by IR accompanied with insufficient insulin secretion, resulting in hyperglycemia that can promote organ damage and serious complications." (PMID 31887984, 2019). "Dysfunction of insulin secretion and hyperglycaemia were commonly found due to damaged β cells of pancreas." (PMID 30800168, 2019). "At a very young age, GK rats first present diabetic symptoms at around 3 weeks of age with hyperglycemia because of impaired beta cell insulin secretion." (PMID 31652915, 2019). "This reflects the antioxidant potential of theaflavin and metformin in long-term control of hyperglycemia through insulin secretion." (PMID 31142215, 2019). "Some studies have suggested insulin administration in patients with severe hyperglycemia at the time of admission in emergency department regardless of their diabetic state." (PMID 31432036, 2019). "Prevention of post-exercise hyperglycemia is based on insulin correction based on an individual’s insulin correction factor (100% or 150%)." (PMID 31546871, 2019). "Findings suggest that bacterial supernatants, especially those derived from virulent gram-negative bacteria (P.g and T.d) in higher concentrations are able to augment insulin secretion in β-cells either in hypo- or hyperglycemia." (PMID 30039349, 2019). "The administration of 0.25 g or 0.5 g of baicalein to high fat diet (HFD) induced mice displayed a significant improvement in glucose tolerance, insulin levels, and hyperglycemia." (PMID 31480505, 2019). "(Fabaceae) bark extract promoted pancreatic β-cell survival, insulin secretion, and enhanced hyperglycemia and hyperlipidemia in glucose-induced diabetic zebrafish." (PMID 31795265, 2019). "This study aims to establish the safety and efficacy of a personalised insulin calculator protocol to estimate the dose of intravenous insulin injection for correction of hyperglycaemia prior to FDG PET/CT." (PMID 30737563, 2019). "Eventually the beta-cells will fail to meet the increasing insulin need, resulting in hyperglycemia and LADA becomes manifest." (PMID 30971952, 2019). "T2DM is characterized by insulin resistance and/or relative defects in insulin serection and resulting hyperglycemia." (PMID 30909971, 2019).
Hyperglycemia (continued). "During the post-operative period hyperglycaemia persisted and subcutaneous insulin therapy was introduced." (PMID 29739729, 2019). "The insulin-release threshold can be adjusted by changing the polymer amount in the coating layers and the insulin release was switched “ON” in response to hyperglycemia and “OFF” to normal glucose levels." (PMID 31119124, 2019). "Safe glucose control, avoiding hypoglycaemia and symptomatic hyperglycaemia can be difficult to achieve with standard subcutaneous insulin therapy in this clinical setting." (PMID 31002426, 2019). "T3cDM in chronic pancreatitis is a result of complex endocrine physiology, mainly as a consequence of insulin deficiency from acinar cell fibrosis resulting in reduced production of insulin with resultant hyperglycaemia." (PMID 31687406, 2019). "This pathway was further investigated in liver of our rat model, in the light of the effects of T2 in alleviating hyperglycemia, improving glucose tolerance and insulin sensitivity during HFD diet, a condition that impairs glucose homeostasis." (PMID 31719576, 2019). "When the patient is warming up, the insulin response increases but hyperglycemia persists for another 1–2 h." (PMID 31208345, 2019). "Of the 61 patients with iatrogenic hypoglycemia after ED insulin administration, 45 and 15 patients received insulin for hyperkalemia and uncomplicated hyperglycemia, respectively." (PMID 31539342, 2019). "In addition to hyperglycemia per se, impaired insulin action might also be an underlying factor that could explain the relationship between hyperglycemia and sarcopenia, because insulin is a well‐known anabolic hormone that contributes to muscle protein synthesis." (PMID 31074209, 2019). "Hyperglycemia is a fundamental characteristic of DM, and results from abnormal functioning of insulin as a hormone regulating glucose metabolism." (PMID 30810587, 2019). "KATP-GOF islets (or WT islets treated with diazoxide), which are permanently in the ‘resting’ state in terms of excitability, [Ca2+]i, and insulin secretion maintain insulin content even in the chronic metabolically stimulated state of hyperglycemia." (PMID 31061431, 2019). "Type 2 diabetes (T2D) is a chronic metabolic disorder characterized by hyperglycemia resulting from defects in insulin secretion, insulin action, or both." (PMID 30901912, 2019). "In insulin-resistant states, hyperglycemia and hyperinsulinemia are in part responsible for enhancing de novo lipogenesis through the activation of both ChREBP and SREBP1c." (PMID 31756997, 2019). "After the initial diagnosis, the patient received intensive insulin therapy to correct hyperglycemia, and he received calcium and vitamin D supplements." (PMID 31574874, 2019). "Due to the competitive interaction of free glucose with glucose transporters, insulin-coupled RBC rapidly released insulin from RBC mediated by the displacement of free glucose under the high glucose level (or hyperglycemia)." (PMID 31817418, 2019). "Intriguingly, the function of NK cells recovered when the blood sugar were corrected by insulin injection in hyperglycemia mice." (PMID 31088566, 2019). "Postprandial glucose fluctuations contribute to approximately 50% of the total hyperglycemia episodes in patients on multiple doses of insulin." (PMID 30622653, 2019). "The ensuing hyperglycemia increases the demand on the beta-cells for a compensatory rise in insulin secretion." (PMID 30971952, 2019). "When hepatic insulin signaling is impaired, gluconeogenesis and glycogenolysis are unleashed, contributing to hyperglycemia and hyperinsulinemia." (PMID 31905727, 2019). "DM comprises a group of metabolic diseases characterized by hyperglycemia, as insulin production by pancreatic β-cells is either insufficient or even absent, and target cells do not respond to circulating insulin." (PMID 31466386, 2019).